RBM14-RBM4 (RBM14-RBM4 readthrough)
Synonyms: COAZ
Gene: Protein-coding gene on chromosome 11 (66,616,626 to 66,646,469, forward strand). Ensembl gene ENSG00000248643.
Genetic constraint (gnomAD): Loss-of-function variants: 7 observed, 28.01 expected, observed/expected ratio (o/e) 0.25, 90% interval 0.14 to 0.47. The upper end of that interval is the gene's LOEUF score, 0.47, which puts it in group 2 of 6, group 1 being the genes least tolerant of losing a copy. Missense variants: 384 observed, 516.15 expected, observed/expected ratio (o/e) 0.74, 90% interval 0.68 to 0.81. Synonymous variants: 232 observed, 225.12 expected, observed/expected ratio (o/e) 1.03, 90% interval 0.93 to 1.15.
Diseases named in the same sentence as RBM14-RBM4 in open-access papers:
RBM14-RBM4 is named in the same sentence as 1 disease in open-access papers, as found by Europe PMC text mining. Sharing a sentence is not in itself a finding about the gene and the disease.
RBM14-RBM4 shares sentences with these, for which no sentence is quoted: pantothenate kinase-associated neurodegeneration (1 paper).